NF1 (neurofibromin 1)
Diseases named in the same sentence as NF1 in open-access papers (continued):
Sharing a sentence is not in itself a finding about the gene and the disease.
multiple endocrine neoplasia type 2 (20 papers, 2005 to 2025). Multiple endocrine neoplasia type 2 (MEN2) is a multiple endocrine neoplasia, a polyglandular cancer syndrome characterized by the occurrence of medullary thyroid carcinoma (MTC), pheochromocytoma (PCC), in one variant, primary hyperparathyroidism (PHPT). "The NF1, RET, and VHL genes, which were identified in the 1990s, are associated with neurofibromatosis type 1 (NF1), multiple endocrine neoplasia type 2 (MEN2A), and von Hipple-Lindau (VHL) disease, respectively." (PMID 39559597, 2024). "In pediatric age it is often associated with genetic syndromes such as Neurofibromatosis 1 (NF1), multiple endocrine neoplasia type 2B (MEN2B) and Cowden syndrome (PTEN mutation), and ganglioneuromas (GNs) may be sometimes the first sign of the disease." (PMID 33785023, 2021). "The transmural diffuse form is strongly associated with genetic syndromes such as Neurofibromatosis 1 (NF1), multiple endocrine neoplasia type 2B (MEN2B) and Cowden syndrome (PTEN mutation), and it can sometimes be the first sign of the disease." (PMID 33785023, 2021). "This includes but is not limited to multiple endocrine neoplasia (MEN) 1, MEN2A, MEN2B, familial medullary thyroid carcinoma (FMTC), Von-Hippel Lindau (vHL) syndrome, Neurofibromatosis type 1 (NF-1), and hereditary paraganglioma-pheochromocytoma syndrome." (PMID 36291833, 2022). "Although a sporadic form exists, the vast majority of PPGLs occur as a manifestation of inherited tumour syndromes such as multiple endocrine neoplasia type 2 (MEN2; RET gene), von Hippel–Lindau (VHL) disease (VHL gene), neurofibromatosis type 1 (NF1; NF1 gene), and hereditary PPGL." (PMID 34356532, 2021). "The whole-life incidence of PH and PGL is high in familial syndromes with these tumors: 1–5% in neurofibromatosis type 1 (NF1), 15–20% in VHL, 30–50% in multiple endocrine neoplasia type 2 (MEN-2), and probably more than 50% in SDHB and SDHD gene mutation carriers." (PMID 17156452, 2006). "Neither NF1 nor DLST are clearly related to medullary thyroid malignancies, but the co-occurrence of both alterations could account for the presence of bilateral PCC and MTC in the same patient, resembling what happens in multiple endocrine neoplasia type 2." (PMID 36760809, 2022).
Anxiety (18 papers, 2013 to 2025). Intense feelings of nervousness, tension, or panic often arise in response to interpersonal stresses. "NF1, in particular, is closely linked with neurodevelopmental disorders such as ADHD and ASD, which are known to heighten vulnerability to anxiety and social difficulties." (PMID 41210128, 2025). "This autistic phenotype and its relationship to common NF1 comorbidities such as anxiety and executive dysfunction will be important to examine in future research." (PMID 34983638, 2022). "When analyzing the EQ-5D-5L, we found that a high proportion of patients reported some degree of pain/discomfort (66% for NF1 and 73% NF2, respectively) and anxiety/depression (61% and 68% for NF1 and NF2, respectively)." (PMID 32642740, 2020). "Anxiety/depression symptoms were higher in females (Ras and TD (p < .021, ηp2 = .03), NS and TD (p < .025, ηp2 = .04)) and in older children (Ras and TD (p < .035, ηp2 = .03), NS and NF1 (p < .035, ηp2 = .04)." (PMID 39764141, 2024). "Anxiety/depression symptoms were higher in children with irritability independently of the group, Ras and TD (p < .001, ηp2 = .12), NS and TD (p < .001, ηp2 = .16) and NS and NF1 models (p < .001, ηp2 = .10)." (PMID 39764141, 2024). "In a univariate regression model, when looking at the two highest scoring survey questions in each survey, “I am embarrassed by the way NF1 affects my physical appearance” (NF1‐AdQOL) was the most important question correlating to HADS anxiety and HADS depression." (PMID 38923593, 2024). "On the other hand, Nf1+/− females developed internalizing symptoms, namely, anxiety-like behaviors." (PMID 37101298, 2023). "Diagnosis of anxiety was slightly higher than expected for NF1, NS, and CFCS." (PMID 35021989, 2022). "Although many patients were aware of the 50% inheritance patterns of NF1, there were still some misconceptions and gaps in the understanding of the genetic basis or pregnancy complications, which influenced their decision‐making and anxiety level around the idea of having a child." (PMID 41216676, 2025). "Overall observations of hyperactivity and anxiety were also noted in NF1+/ex42del minipigs, which may correlate with symptoms of NF1 as there is a high prevalence of attention-deficit/hyperactivity disorder (ADHD) and autistic traits reported in children with NF1." (PMID 33669386, 2021). "Neurofibromatosis 1 (NF1) is a genetic disorder that is accompanied by psychiatric comorbidities such as depression, anxiety, and attention-deficit hyperactivity disorder (ADHD) in more than half of the patients." (PMID 35004058, 2021). "Individuals with NF1 and NF2 have low quality of life, and this correlates with pain, anxiety, and depression, which are prevalent in NF1 and NF2." (PMID 32642740, 2020). "Our EPM results suggested that Nf1 OPG mice do not show increased levels of anxiety-like behaviors according to the classic indicators involving behaviors emitted in the open arms." (PMID 23762458, 2013). "Importantly, anxiety-related behaviors in male and female rats were not affected by intrathecal Nf1 editing, demonstrating that our reductionist approach of symptom-specific modeling of a multi-faceted disease may permit mechanistic studies into NF1 pain as well as other neurological symptoms." (PMID 28837387, 2018).
meningioma (18 papers, 2006 to 2025). A generally slow growing tumor attached to the dura mater. "NF1/2 mutation analyses were also performed to explore the prognostic value of such mutations in these atypical meningiomas." (PMID 33809258, 2021). "We also wanted to explore the prognostic value of NF1/2 mutations in these WHO grade II atypical meningiomas." (PMID 33809258, 2021). "Other common driver mutations in our cohort such as CDKN2A, ARID1A, BRCA1, NF1, AKT1, SMO, PIK3CA have similarly been noted in various prior sequencing studies of meningiomas." (PMID 31191822, 2019). "There is no strong evidence for an association between NF1 and meningioma; however, the incidence of NF1 in meningioma patients from the meta-analysis is much higher than the background incidence at 1 in 2600 to 3000." (PMID 39612013, 2024). "Meningiomas occur with greater frequency in patients with germline mutations of genes such as type-2 neurofibromatosis (NF2), type-1 neurofibromatosis (NF1, 19–24% of adolescent meningiomas), type-1 multiple endocrine neoplasia (MEN1), SMARCB1, LZTR1, or SMARCE1 genes." (PMID 37760490, 2023). "Data from 20 studies (2011–2023), including 1010 pediatric meningioma cases, were analyzed to assess PFS and OS stratified by WHO grade, NF1/NF2 status, extent of resection (EOR), and adjuvant radiotherapy." (PMID 39779595, 2025). "CDKN2A, ARID1A, BRCA1, NF1, and AKT1 were also commonly identified in meningioma samples across the cohort." (PMID 31191822, 2019).
fragile X syndrome (17 papers, 2012 to 2025). A genetic syndrome caused by mutations in the FMR1 gene which is responsible for the expression of the fragile X mental retardation 1 protein. "The mTOR signaling pathway is a convergent pathway that is disturbed by genetic variations in the TSC1 and TSC2 (TSC), PTEN (Bannayan-Riley-Ruvalcaba syndrome, Lhermite-Duclos syndrome, and Cowden syndrome), FMRP (fragile X syndrome), and NF1 (neurofibromatosis type 1) genes." (PMID 36732866, 2023). "mTOR hyperactivity was observed for example in fragile X syndrome (FXS), neurofibromatosis 1 (NF1), tuberous sclerosis, and Opitz BBB/G syndrome." (PMID 34204880, 2021). "The other 48 articles focused on specific ID‐related disorders, in which xeroderma pigmentosum (XP) was the most common (n = 12), followed by DS (n = 11), NF1 (n = 8), Fanconi anemia (FA) (n = 4), Fragile X syndrome (FXS) (n = 2), and Nijmegen breakage syndrome (NBS) (n = 2)." (PMID 38686623, 2024).
low grade glioma (17 papers, 2016 to 2025). A grade I or grade II glioma arising from the central nervous system. "Phase 3 COG trials are currently underway to directly compare standard chemotherapy versus MEK inhibitors in NF1 associated and sporadic low-grade gliomas in the upfront as well as recurrent setting." (PMID 35480100, 2022). "Predisposition syndromes, such as NF-1 or TSC, are associated with specific types of low-grade glioma, which occur during childhood." (PMID 34828788, 2021). "Herein, we leverage genetically engineered mouse models and human biospecimens to define the axis in which neurons, T cells, and microglia interact to govern Neurofibromatosis-1 (NF1) low-grade glioma (LGG) growth." (PMID 32358581, 2020). "Drugs targeting MEK inhibition (MEKi) have been selected for testing in NF1- and BRAF-altered paediatric low-grade gliomas (pLGG) and for PAs in particular." (PMID 37033188, 2023). "In addition to NF1-PN, there are ongoing studies to further investigate the efficacy of MEK inhibitors in other NF1-related tumors, including cutaneous neurofibromas and low-grade glioma." (PMID 37328781, 2023).
non-small cell lung carcinoma (17 papers, 2013 to 2025). A group of at least three distinct histological types of lung cancer, including non-small cell squamous cell carcinoma, adenocarcinoma, and large cell carcinoma. "The trial NCT03232892 aimed to investigate the efficacy of trametinib in patients diagnosed with non-small cell lung cancer and bearing NF1 mutations." (PMID 41170454, 2025). "Mutations in RASA1 and NF1 co-occur in human non-small cell lung cancer, which may reflect independent mechanisms by which RASA1 and NF1 inhibit RAS or the clonal diversity within these tumors that preferentially selects one of these mechanisms." (PMID 33435458, 2021). "We are not aware of other studies or case reports detailing the response of NF1-altered non-small cell lung cancer to MEK inhibitors." (PMID 41170454, 2025). "It was also confirmed that miR-641 contributes to erlotinib resistance in non-small-cell lung cancer by targeting NF1 and regulating ERK signaling." (PMID 32210717, 2020). "In non-small cell lung cancers (NSCLC), mutations in NF1, MET, and ERBB2 account for up to 13% of tumors analyzed by molecular profiling, and elevation in MAPK and PI3K activity was observed in a large proportion of cases." (PMID 30359271, 2018). "It was observed that most non-small cell lung cancer cases with NF1 mutation do not exhibit co-mutations." (PMID 41170454, 2025). "Moreover, it has been reported that the up-regulation of miR-641 induces erlotinib resistance by inhibiting NF1 in non-small-cell lung cancer." (PMID 38006396, 2023). "One of these variants (c.2374C > T; p.L792F) was also found in all patients but the significance of these mutations in the NF1 tumor suppressor gene in non-small cell lung cancer has not been demonstrated." (PMID 35884384, 2022). "Non-small cell lung carcinoma (NSCLC), the leading cause of cancer mortality worldwide, has known driver mutations of nodes on this pathway in ~75% of cases, including: ~30% KRAS, ~11% EGFR, ~7% BRAF and ~11% NF1 mutations." (PMID 31182717, 2019). "Specifically, although there is no clear association reported with NF1, altered glutathione (GSH) metabolism is thought to be a major mechanism of chemoresistance and GSH levels are reportedly elevated in non-small cell lung cancer." (PMID 25884485, 2015).
aneurysm (16 papers, 2011 to 2025). Bulging or ballooning in an area of an artery secondary to arterial wall weakening. "Patients with NF1 mutations exhibit several vascular abnormalities, such as aneurysms or stenosis of the aortic, renal, and mesenteric arteries." (PMID 30828344, 2019). "NF1 is clinically associated with a pleiotropic array of vascular abnormalities including stenosis, malformations, aneurysms, and hypertension." (PMID 23145129, 2012). "Interestingly, fibrous tissue around the left colic artery stained positive for S-100 protein, suggesting that neurofibroma from NF1 might have been associated with the rupture of these aneurysms due to weakened integrity of the vascular walls." (PMID 30673931, 2019). "Vascular anomalies, including arterial stenosis and aneurysms, are notable in NF1 and BS, whereas cardiac fibromas are typical in GS." (PMID 39641826, 2025). "All NF1-related SRA aneurysms were observed in the arterial trunk and had ruptured at the time of diagnosis." (PMID 35922696, 2022). "The association of NF-1 with CVD is described to result in a wide range of pathologies, such as cerebral ischemia, aneurysms and Moyamoya Syndrome (MMS)." (PMID 33395412, 2021). "The spectrum of vasculopathy in NF-1 includes aneurysms, stenosis, and medium- and large-vessel arteriovenous malformations." (PMID 34239644, 2021). "Indeed, NF1 causes intimal proliferation, thinning of the muscle layer and fragmentation of the elastic layer that may have promoted the vascular occlusion and later on, the aneurysm occurrence." (PMID 24499535, 2014). "Arterial stenosis or aneurysms have been variously studied, but the association with NF1 has not been firmly established." (PMID 36340543, 2022). "In addition, some studies have demonstrated cardiovascular anomalies in NF1, such as moyamoya disease, internal carotid artery occlusion or stenosis, cerebral arteriovenous fistula, dissection, or intracranial aneurysms." (PMID 34325735, 2021). "Taken together, the weakness of the arterial vessel wall inherent to NF1, and the blood flow change caused by IMA deficit, may have resulted in these secondary LCA aneurysms." (PMID 30673931, 2019). "The incidence of vascular involvement of NF1, mainly stenosis and aneurysms, is approximately 3.6%." (PMID 25688270, 2015).
dermal neurofibroma (16 papers, 2011 to 2023). A dermal neurofibroma is a neurofibroma that occurs in situ of the skin. "NF1 is caused by pathogenic variants in NF1 gene on chromosome 17q11.2 and characterized by skin pigmentation anomalies such as café-au-lait spots and freckling, as well as dermal neurofibromas." (PMID 37041514, 2023). "Other NF1-associated features such as skin-fold freckling and Lisch nodules occur later during childhood whereas dermal neurofibromas are rare in young children and usually only arise during early adulthood." (PMID 34928431, 2022). "Interestingly, the formation of NF-1-associated dermal neurofibromas has previously been reported to be microenvironment-dependent, highlighting a potential role for NF-1 in organizing the tumor microenvironment of cancers of the nervous system." (PMID 31632393, 2019). "Biallelic NF1 inactivation in benign dermal neurofibromas is a known phenomenon, and it is supposed that all lesional tissues develop from a second hit that may occur in utero or during the entire postnatal life." (PMID 37569527, 2023). "First, genotype–phenotype correlation studies in people with NF1 have revealed intriguing associations; the most striking of which is the finding that individuals with p1809 codon mutations do not develop dermal neurofibromas." (PMID 28066715, 2016). "Finally, the level of sAXL was significantly increased in patients with plexiform tumors compared to patients with only dermal neurofibromas, further supporting the role of sAXL as a marker for NF1 related tumor burden." (PMID 25551830, 2014). "Patients with a microdeletion of the NF-1 locus have higher numbers of discrete dermal neurofibromas at earlier ages and might have a higher incidence of MPNSTs than the overall NF-1 population." (PMID 25317349, 2014). "Two different populations of S100β+ cells (presumably terminally differentiated Schwann cells) have been demonstrated within in vitro cultures obtained from dermal neurofibromas, indicating that both NF1 Schwann cell subtypes (+/−) and (−/−) coexist in these tumors." (PMID 22550514, 2012). "In dermal neurofibromas, local trauma can be a factor in the development of the tumors and it has been suggested that dermal neurofibromas could be hyperplastic instead of neoplastic lesions, due to a poorly regulated wound healing in NF1 haploinsufficient tissues." (PMID 22550514, 2012). "After developing the MMPA calculations presented here, we re-analyzed a set of 29 dermal neurofibromas with the newly established microsatellite multiplex PCR conditions and obtained data regarding the percentage of non-AI cells within these tumors and the NF1 locus copy-number." (PMID 22916147, 2012).
desmoplastic melanoma (16 papers, 2017 to 2025). A melanoma of the skin characterized by a proliferation of atypical spindled melanocytes in the dermis, in a background of abundant collagen. "Especially in desmoplastic melanoma, NF1 gene mutations are commonly observed with frequencies of up to 93%." (PMID 34065301, 2021). "Although NF1 mutations have been associated with desmoplastic melanoma in the general population, only one case has been reported as a desmoplastic melanoma but interestingly sharing some morphologic characteristics with MPNSTs." (PMID 33530415, 2021). "In contrast, desmoplastic melanoma frequently harbors NF1 mutations." (PMID 39564955, 2024).
neuroendocrine tumors (16 papers, 2005 to 2025). "Gastrointestinal malignancy was reported to be associated with NF1 patients, with neuroendocrine tumors being the most prevalent." (PMID 16042772, 2005). "An autosomal dominant disease arising from the mutation of NF1 on chromosome 17q11, NF1 presents with spinal malformations, vascular malformations and malignant and benign tumors in the peripheral and central nervous systems with 2% of patients also having neuroendocrine tumors." (PMID 37568540, 2023). "Neuroendocrine tumors arising in the ampullary or periampullary lesions are the most common and characteristic gastrointestinal manifestations of NF-1." (PMID 28835241, 2017). "In patients with NF-1, neuroendocrine tumors sometimes develop: the most common tumor is somatostatinoma arising in the peri-ampullary and duodenal region." (PMID 22824559, 2012). "While models for genes of cluster 2 PPGL (RET, NF1, and TMEM127) have been studied since 1992, these models are suboptimal as they are generally associated with development of additional unrelated non-neuroendocrine tumors." (PMID 36428741, 2022). "A completed phase II trial evaluated whether the selected drugs, sunitinib or everolimus, based on the defective gene would result in a better tumor response to patients with advanced neuroendocrine tumors, including NF1 (Clinicaltrials.gov ID: NCT02315625)." (PMID 34566848, 2021). "Patients with neurofibromatosis-1 (NF-1) sometime develop neuroendocrine tumors (NET)." (PMID 22824559, 2012). "Everolimus is now also being used to treat neuroendocrine tumours, gastric cancer, TSC- and neurofibromin 1 (NF1)-related tumours." (PMID 29301334, 2018). "However, mutations in various genes related to TKs were detected in the tumor samples (JAK3, NRAS, NTRK2, NF1, SETD2) suggesting frequent alteration of TK pathways for neuroendocrine neoplasms." (PMID 36743926, 2022). "As in our case, NF1 can be related to neuroendocrine tumors that will progress if not managed early in the course of the disease." (PMID 16042772, 2005). "ALT was also identified in a single malignant phyllodes tumor, although ALT was uniformly absent in the remaining NF1-associated tumors (e.g. GIST, neuroendocrine tumors, and glomus tumors), suggesting that ALT in NF1-associated tumors is associated with a malignant phenotype." (PMID 31462295, 2019). "He had no family history of neuroendocrine tumors, gastrointestinal cancers, or inherited syndromes (e.g., MEN1, NF1)." (PMID 40869648, 2025).